STX7 (syntaxin 7)
Description:
May be involved in protein trafficking from the plasma membrane to the early endosome (EE) as well as in homotypic fusion of endocytic organelles. Mediates the endocytic trafficking from early endosomes to late endosomes and lysosomes.
Tractability: Antibody: its Gene Ontology location is reachable by antibodies, with high confidence; UniProt predicts a signal peptide or a membrane-spanning region. PROTAC: ubiquitination databases record sites on it; its protein half-life has been measured.
Gene: Protein-coding gene on chromosome 6 (132,445,867 to 132,513,999, reverse strand). Ensembl gene ENSG00000079950.
Subcellular location: Early endosome membrane
Subcellular location (Human Protein Atlas): Lysosomes
Gene Ontology:
Molecular function: chloride channel inhibitor activity; protein binding; SNARE binding; syntaxin binding; SNAP receptor activity
Biological process: organelle assembly; organelle localization; positive regulation of receptor localization to synapse; positive regulation of T cell mediated cytotoxicity; regulation of protein localization to plasma membrane; intracellular protein transport; membrane fusion; vesicle-mediated transport
Cellular component: azurophil granule; early endosome; endocytic vesicle; endosome; extracellular exosome; immunological synapse; late endosome; lysosomal membrane; lysosome; perinuclear region of cytoplasm; plasma membrane; recycling endosome; tertiary granule; vesicle; synaptic vesicle; early endosome membrane; membrane; secretory vesicle
Genetic constraint (gnomAD): Loss-of-function variants: 14 observed, 24.34 expected, observed/expected ratio (o/e) 0.58, 90% interval 0.38 to 0.9. The upper end of that interval is the gene's LOEUF score, 0.9, which puts it in group 3 of 6, group 1 being the genes least tolerant of losing a copy. Missense variants: 215 observed, 235.16 expected, observed/expected ratio (o/e) 0.91, 90% interval 0.82 to 1.02. Synonymous variants: 90 observed, 80.98 expected, observed/expected ratio (o/e) 1.11, 90% interval 0.94 to 1.32.
Homologues: Orthologues: chimpanzee STX7 (99% identical), macaque STX7 (98% identical), mouse Stx7 (94% identical), rabbit STX7 (89% identical), guinea pig STX7 (87% identical), dog STX7 (84% identical), rat Stx7 (84% identical), pig STX7 (79% identical), tropical clawed frog stx7 (68% identical), zebrafish stx7l (57% identical), Drosophila melanogaster Syx7 (42% identical), Caenorhabditis elegans syx-7 (30% identical). Paralogues in human: STX12 (54% identical), TSNARE1 (27% identical), STX16 (25% identical), STX1A (23% identical), STX3 (23% identical), STX2 (23% identical), STX1B (22% identical), STX4 (21% identical), STX5 (20% identical), STX11 (18% identical), STX17 (18% identical), STX19 (17% identical).
Diseases named in the same sentence as STX7 in open-access papers:
STX7 is named in the same sentence as 13 diseases in open-access papers, as found by Europe PMC text mining. Sharing a sentence is not in itself a finding about the gene and the disease. The quoted sentences say what the papers report.
breast carcinoma (1 paper, 2024). "Thus, increased levels of STX7 are implicated as a major contributing factor in breast cancer cell invasion." (PMID 39057719, 2024). "Although little research exists on the role of STX7 in breast cancer, a recent in vitro study highlighted the involvement of STX7 as a promoter of invadopedia (i.e., matrix-degrading structures) formation during cancer cell invasion." (PMID 39057719, 2024).
hepatocellular carcinoma (1 paper, 2025). A malignant tumor that arises from hepatocytes. "STX7 promotes EMT and tumor progression via NF-κB signaling, with a strong association to macrophage infiltration in cancers, including hepatocellular carcinoma, highlighting its potential as a prognostic biomarker and therapeutic target." (PMID 40999361, 2025). "Functional experiments demonstrated that STX7 knockout suppressed hepatocellular carcinoma proliferation and migration, while inhibiting epithelial-mesenchymal transition (EMT) via NF-κB signaling." (PMID 40999361, 2025). "Syntaxin-7 (STX7), a membrane trafficking-related gene, has been implicated in various cancers, but its specific role in hepatocellular carcinoma remains unclear." (PMID 40999361, 2025).
melanoma (1 paper, 2019). A malignant, usually aggressive tumor composed of atypical, neoplastic melanocytes. "High expression of syntaxin 7 in melanoma tissues was shown to be inversely proportional to tumor growth and aggressiveness, while a proteomics-based study identified several molecules in metastatic tissue, potentially promising regarding predictions of metastatic disease." (PMID 31803364, 2019).
Obesity (1 paper, 2026). Accumulation of substantial excess body fat. "Compared to controls, immune‐related pathways such as adaptive immunity and leukocyte‐mediated processes (e.g., STX7, HPX, LAMP1, C5) were upregulated in obesity." (PMID 41077621, 2026). "Lastly, our study identifies several differently regulated proteins whose role in obesity and adipose tissue is poorly known, such as ANXA8, DDX39B, STX7, SYNCRIP, SYNGR2, and PAK2." (PMID 41077621, 2026). "Thus, while the role of STX7 in obesity has not been previously recognized, our results suggest that STX7 may contribute to the VAT inflammation in obesity." (PMID 41077621, 2026).
cancer (3 papers, 2024 to 2025). A tumor composed of atypical neoplastic, often pleomorphic cells that invade other tissues. "STX7 was significantly upregulated in a wide range of cancer types and was associated with poor prognosis." (PMID 40999361, 2025). "To identify cancer-related markers linked to STX7, we conducted GSEA on DEGs between the low and high STX7 subgroups in each cancer type." (PMID 40999361, 2025). "Furthermore, the KRAS signaling pathway, IL6/JAK/STAT3 pathway, and IL-2/STAT5 pathway were strongly linked to STX7 expression in cancer." (PMID 40999361, 2025). "Building on these findings, we conducted a pan-cancer analysis of STX7 to clarify its expression patterns, prognostic associations, functional enrichment, and immune infiltration characteristics, aiming to evaluate its potential as a biomarker and immunotherapy target." (PMID 40999361, 2025). "The ROC curve indicates that STX7 could serve as a potential diagnostic biomarker for certain cancers." (PMID 40999361, 2025). "Additionally, cancers exhibiting a positive correlation between STX7 and ImmuneScore also showed a positive association with most immune checkpoint genes." (PMID 40999361, 2025). "A comprehensive analysis of STX7 mRNA expression across cancer types was performed using data from the TCGA and GTEx databases." (PMID 40999361, 2025). "In this study, we performed a pan-cancer multi-omics analysis of STX7 using integrated datasets from tumor and normal tissues to elucidate its associations with expression patterns, clinical parameters, and patient prognosis." (PMID 40999361, 2025). "To investigate the immunological role of STX7 within the cancer microenvironment, we calculated the ESTIMATE score for STX7 across a range of cancer types." (PMID 40999361, 2025). "As expected, we observed the expression of STX7 in PDAC is higher than cancer adjacent, which was consistent with our previous findings and suggested STX7 is the risk factor of PDAC." (PMID 40789825, 2025). "We chose STX7 for an in-depth investigation to explore its expression patterns, prognostic significance, enriched pathways, and immune infiltration across various cancers." (PMID 40999361, 2025). "Mechanistically, STX7 promotes invadopodia formation during cancer invasion by modulating MT1-MMP trafficking." (PMID 40999361, 2025). "To further investigate its prognostic value, we analyzed 33 cancer types from the TCGA database and examined the correlation between STX7 expression and various survival outcomes, including OS, DSS, PFS, and DFS." (PMID 40999361, 2025). "Nonetheless, our understanding of the link between STX7 and cancer progression remains limited, necessitating further studies to elucidate its mechanisms, functions, and therapeutic applications." (PMID 40999361, 2025). "While its physiological role is well established, recent evidence suggests that STX7 dysregulation may contribute to tumorigenesis and immune remodeling in a cancer-type-specific manner." (PMID 40999361, 2025). "This analysis revealed significant alterations in STX7 expression across 23 cancer types." (PMID 40999361, 2025). "Notably, genes such as HAVCR2, PDCD1LG2, CD274, and TIGIT exhibited the strongest positive correlations with STX7 across more than 20 cancer types, suggesting a role for STX7 in immune checkpoint-mediated regulation." (PMID 40999361, 2025). "Additionally, we examined potential genomic alterations in STX7 across specific cancers." (PMID 40999361, 2025). "suggesting that STX7 may contribute to cancer progression via EMT." (PMID 40999361, 2025). "There has been no pan-cancer analysis examining the immunological function and prognostic significance of STX7 so far." (PMID 40999361, 2025). "To further confirm the conclusion of genetic MR analysis, we compared the expression of STX7 and LUM in paired human cancer specimens and adjacent non-cancerous tissues based on TCGA by GEPIA 2.0." (PMID 40789825, 2025).
infection (3 papers, 2009 to 2026). The state of being infected such as from the introduction of a foreign agent such as serum, vaccine, antigenic substance or organism. "VAMP7 and Vti1B were localized to the PVM within 30 min post-infection, suggesting potential roles during invasion, while VAMP8 and Stx7 appeared later around 24 h post infection (hpi), coinciding with increased nutrient acquisition." (PMID 41972675, 2026). "STX7 and SCAMP1 transcript levels, which generally increased over the time course, were only significantly increased in expression in N'Dama relative to pre-infection and at 25 dpi N'Dama had 1.4-fold higher levels of STX7 mRNA relative to Boran." (PMID 19409086, 2009). "At 25 dpi, in particular, when maximum levels of STX7 mRNA were observed in N'Dama (2.2-fold, P = 0.0013) compared to pre-infection, N'Dama had 1.4-fold higher levels of STX7 mRNA relative to Boran (P = 0.0484)." (PMID 19409086, 2009). "Collectively, we verified that two membrane trafficking proteins, STX7 and SNAP23, indirectly interact with MAAP2 during both wtAAV2 infection and rAAV2 production." (PMID 39807420, 2025).
tumor (2 papers, 2019 to 2025). "STX7 is frequently upregulated in multiple malignancies and has been linked to tumor progression and adverse prognosis." (PMID 40999361, 2025). "In conclusion, STX7 is overexpressed in tumor tissue, associated with poor prognosis, and plays a role in immune regulation, evasion, and tumor progression." (PMID 40999361, 2025). "STX7 expression was positively correlated with tumor mutational burden (TMB) in ESCA and THYM and with microsatellite instability (MSI) in COAD, READ, and UCEC." (PMID 40999361, 2025). "This indicates that STX7 expression modulates the immune microenvironment via chemokine signaling, likely contributing to tumor progression by altering the immune landscape." (PMID 40999361, 2025). "In vivo experiments demonstrated that STX7 silencing significantly reduced subcutaneous xenograft tumor growth and macrophage infiltration compared to controls." (PMID 40999361, 2025). "Collectively, these results highlight STX7 as a potential therapeutic node in NF-κB signaling, offering opportunities to attenuate tumor-promoting inflammation and reinvigorate anti-tumor immune responses." (PMID 40999361, 2025). "Although emerging evidence implicates STX7 in immune regulation within the tumor microenvironment, its role in immune escape in HCC remains insufficiently characterized." (PMID 40999361, 2025). "Single-cell RNA-seq and spatial transcriptomic analyses further revealed that STX7 is predominantly expressed in macrophages within the HCC microenvironment, likely corresponding to tumor-associated macrophages (TAMs)." (PMID 40999361, 2025). "Enrichment analysis further underscored the potential role of STX7 in immune evasion and tumor progression." (PMID 40999361, 2025). "These pathways imply that STX7 may orchestrate both immune activation and suppression, thereby altering the equilibrium between tumor immune surveillance and immune escape." (PMID 40999361, 2025). "Our single-cell and spatial transcriptomic analyses revealed that STX7 is predominantly expressed in monocyte-derived macrophages in HCC, with dynamic upregulation during differentiation and co-localization with CD14 and CD68 in tumor regions." (PMID 40999361, 2025). "Although subcutaneous xenograft models were used to assess tumor growth, the absence of orthotopic liver and lung metastasis models may limit physiological relevance, and future studies will incorporate these models to better evaluate the in situ and metastatic roles of STX7." (PMID 40999361, 2025).
STX7 also shares sentences with these, for which no sentence is quoted: cutaneous leishmaniasis (1 paper); leishmaniasis (1); lysosomal storage disorder (1); metastatic disease (1); neuroblastoma (1); schizophrenia (1).